CXCL11 (C-X-C motif chemokine ligand 11)
Diseases named in the same sentence as CXCL11 in open-access papers (continued):
Sharing a sentence is not in itself a finding about the gene and the disease.
giant cell arteritis (1 paper, 2022). "For example, in giant cell arteritis (GCA), another large vessel vasculitis, CXCL9, CXCL10, and CXCL11 were reported to mediate macrophage infiltration in vascular lesions." (PMID 35172901, 2022).
Hashimoto thyroiditis (1 paper, 2022). An autoimmune disorder caused by the production of autoantibodies against thyroid tissue. "Recent studies indicate that chemokines CXCL9, CXCL10 and CXCL11, induced by INF-γ, may play an important role in the early development of Hashimoto’s thyroiditis." (PMID 36139446, 2022).
Headache (1 paper, 2023). Cephalgia, or pain sensed in various parts of the head, not confined to the area of distribution of any nerve. "Headache was associated with significant increase in CXCL10, CXCL11, MCSF, MCP-2 and TNF-alpha, while fatigue was associated with significant increases in CXCL10, MCP-4 and TNF-α." (PMID 38235127, 2023).
hemorrhagic (1 paper, 2025). "The downregulation of chemokines, CXCL10 and CXCL11, would reduce the recruitment of immune cells, including M1 macrophages, to areas with thrombotic or hemorrhagic plaques." (PMID 40969943, 2025).
hepatitis B (1 paper, 2021). "Studies have shown that prevaccination levels of CXCL11 and CXCL12 in healthy individuals and CXCL13 in HIV+ subjects may predict hepatitis B-vaccine response." (PMID 33431890, 2021).
HIV encephalitis (1 paper, 2020). "The chemokines CXCL10 and CXCL11 were assessed because we found their levels to be elevated in the brain of HIVgp120tg mice and CXCL10 has been linked to neuronal dysfunction and found to be overexpressed in the CNS of HIV encephalitis (HIVE) patients." (PMID 32727588, 2020).
Hyperglycemia (1 paper, 2023). An increased concentration of glucose in the blood. "Our findings may align with previous studies showing that hyperglycemia promotes the expression of CXCL10 and CXCL11 on Schwann cells, recruiting CXCR3‐expressing CD8+ lymphocytes and leading to apoptosis of the Schwann cells." (PMID 37021432, 2023).
hyperthyroidism (1 paper, 2021). Overactivity of the thyroid gland resulting in overproduction of thyroid hormone and increased metabolic rate. "A prevalent Th1-immune response (not related to the hyperthyroidism per se, but to the autoimmune process) is reported in the immune-pathogenesis of GD and GO; Th1-chemokines (CXCL9, CXCL10, CXCL11) and the (C-X-C)R3 receptor are crucial in this process." (PMID 33935970, 2021).
hypertriglyceridemia (1 paper, 2023). A laboratory test result indicating elevated triglyceride concentration in the blood. "In that period, triglyceride levels negatively correlated with CXCL10 and CXCL11, both chemokines known to cause hypertriglyceridemia." (PMID 36692327, 2023).
immunodeficient diseases (1 paper, 2022). "The functional capacities of the highly expressed DEGs in the Chinese Simmental cattle mainly focused on inflammatory diseases (CXCL9 and FCRL1), immunodeficient diseases (ADM2, CCL5, and CAMKV), carcinoma (CXCL11, JAKMIP2, GZM, and DNAAF1), and GTP binding and GTPase activity (NUGGC)." (PMID 35495650, 2022).
iron-overload (1 paper, 2025). "On the one hand, the decreased CXCL11 level, a potent chemoattractant for T cells acting, expressed by LAMs in iron-overload mice, may contribute to fewer effector T cells in AML." (PMID 40881683, 2025).
laryngeal carcinoma (1 paper, 2022). Carcinoma that arises from the laryngeal epithelium. "Prognosis-related IRGs were then explored by univariate cox regression analysis and correction of clinical factors, AQP9, CXCL11, IGHV4.31, PDGFA and ZAP70 were significantly correlated to laryngeal cancer prognosis." (PMID 35477402, 2022).
leprosy (1 paper, 2021). Leprosy is a chronic infectious disease affecting primarily the skin and peripheral nervous system. "As for differentiating leprosy per se vs. ODD, genes IDO1, BLK (exon 11), CD38, CXCL11, and SLAMF7, all had an area under the curve (AUC) of at least 96% with their lower bound 97% confidence intervals above 90%." (PMID 34695167, 2021).
leptospirosis (1 paper, 2024). A contagious bacterial infection caused by spirochetes of the genus Leptospira. "The correlation analysis of detected chemokines CXCL11, CXCL9, CCL3, and CCL2 helps to clarify the role of each cytokine in leptospirosis." (PMID 39534703, 2024).
mastitis (1 paper, 2024). Inflammation of breast tissue during lactation or postpartum due to an obstructed duct or infection. "Chemokines MCP-1 and CXCL11 were also found in greater concentrations in milk produced by women with SCM or CM the week of mastitis detection compared to that produced by healthy controls." (PMID 39896819, 2024).
metabolic syndrome (1 paper, 2024). A cluster of metabolic risk factors for CARDIOVASCULAR DISEASES and TYPE 2 DIABETES MELLITUS. "Additionally, the inverse associations of CXCR3+ T lymphocytes with dyslipidemia suggest their recruitment to adipose tissue by CXCL10 or CXCL11." (PMID 39109081, 2024).
metastasis (1 paper, 2020). The spread or migration of cancer cells from one part of the body (where they first appeared) to another. "Moreover, expression of individual genes in this panel, including IL18RAP, CXCL11, FCER1G, CSF3R and IL2RG were strongly linked to distant metastasis, lymph node metastasis, tumor stage, clinical stage or pathologic grade." (PMID 33049716, 2020).
Miscarriage (1 paper, 2025). A pregnancy that ends at a stage in which the fetus is incapable of surviving on its own, defined as the spontaneous loss of a fetus before the 22th week of pregnancy. "Further research on 17 core enriched genes expressed at the MFI indicated that CXCL11, MMP10, FOS, FOSB, LY96, and NCF2 may be closely related to miscarriage." (PMID 41232126, 2025).
multinodular goiter (1 paper, 2021). Nodular goiter characterized by more than one discrete tissue mass. "Another study found that circulating CXCL9 and CXCL11 levels were significantly elevated in patients with AIT compared with euthyroid controls or patients with multinodular goiter." (PMID 34868029, 2021).
myocardial infarction (1 paper, 2024). Gross necrosis of the myocardium, as a result of interruption of the blood supply to the area, as in coronary thrombosis. "Five proteins deregulated in homozygous LAV-BPIFB4 carriers (e.g. CXCL11, CSF-1, SLAMF7, IL-10RB and TNFRSF9) emerged from a recent proteome-based CV risk model as the top factors predicting myocardial infarction event." (PMID 38468336, 2024).
papilloma (1 paper, 2020). A benign epithelial neoplasm that projects above the surrounding epithelial surface and consists of villous or arborescent outgrowths of fibrovascular stroma. "In the K17KO papillomas, while we found significant induction of CXCL9 and CXCL10, there was a significant reduction in CXCL11 RNA level compared to WT papillomas (p = 0.0002)." (PMID 31968015, 2020). "When we blocked CXCR3, the papillomas in K17KO mice increased significantly in size, despite a reduction in CXCL11 level." (PMID 31968015, 2020).
periodontitis (1 paper, 2021). An acute or chronic inflammatory process that affects the tissues that surround and support the teeth. "The CCL13 (also called Monocyte Chemoattractant Protein 4- MCP4) is involved in the inflammatory process of several diseases and its levels are increased in the gingival crevicular fluid (GCF) of patients with periodontitis whereas CXCL11 is related with Th1 cell accumulation in inflamed mucosa." (PMID 35048045, 2021).
prostate (1 paper, 2015). "Moreover, luciferase assays and quantitative polymerase chain reaction (qPCR) were used to study how chemokines CXCL11 and CXCL12 regulate androgen-regulated genes (ARGs) in LNCaP prostate-tumor cells." (PMID 25884570, 2015).
Ramsay-Hunt syndrome (1 paper, 2019). "The same holds true for VZV as VZV meningitis patients but not patients with VZV encephalitis or Ramsay Hunt syndrome had significantly elevated CXCL11 CSF levels." (PMID 30777092, 2019).
renal fibrosis (1 paper, 2022). A final common manifestation of a wide variety of chronic kidney diseases characterized by glomerulosclerosis and tubulointerstitial fibrosis. "Reportedly, sorafenib, an xCT inhibitor, can inhibit the TGF-β/Smad3-induced EMT signaling and suppress the CXCR3/CXCL11-mediated macrophage infiltration, ameliorating renal fibrosis." (PMID 35655759, 2022).
retinitis (1 paper, 2022). Inflammation of the retina. "When mRNA expression pattern was compared between the two groups it showed that the expression of CXCL9 and CXCL10 was significantly higher in case of retinitis patients whereas that of CXCL11 was higher in case of the patients with gastro-enteric disease." (PMID 35538132, 2022).
schistosomiasis (1 paper, 2012). An infectious disease caused by parasitic trematodes of the genus Schistosoma that colonize human blood vessels and release eggs that can cause granulomatous reactions leading to acute (swimmer's itch or acute schistosomiasis syndrome) or chronic disease. "The results showed that CXCL9 and CXCL10, but not CXCL11 or CXCL4, significantly inhibited the gene expressions of Col1α1, Col3α1 and α-SMA, indicating the potential anti-fibrosis effect of CXCL9 and CXCL10 in schistosomiasis." (PMID 22905138, 2012).
scrapie (1 paper, 2016). A fatal disease of the nervous system in sheep and goats, characterized by pruritus, debility, and locomotor incoordination. "Cxcl11 was in fact found previously to be elevated in the late stages of scrapie." (PMID 27046083, 2016). "Cxcl11 and Cxcl1 were the only genes upregulated by BE and not by scrapie in these samples." (PMID 27046083, 2016).
serous ovarian tumors (1 paper, 2018). "However, such response of ERβ does not seem to occur in OC cells, as suggested by the limited action of ERβ to regulate CXCR7, its poor recruitment to CXCR7 gene, and its lack of correlation with CXCL11 in high serous ovarian tumors." (PMID 30051594, 2018).
skin squamous cell carcinoma (1 paper, 2022). A carcinoma arising from the squamous cells of the epidermis. "In skin squamous cell carcinomas, upregulation of ETV1 was sufficient to induce most CAF effectors upregulated by fibroblast growth factor (FGF), which could promote the secretion of multiple chemokines with macrophage-recruiting activity including CXCL1, CXCL10, and CXCL11." (PMID 35860243, 2022).
skin tumor (1 paper, 2023). "K17 is known to promote CXCL10 and CXCL11 expression in skin tumor keratinocytes." (PMID 38140561, 2023).
spinal injury (1 paper, 2021). A injury that involves the vertebral column. "The levels of cytokines CXCL5, CCL11, CXCL11, IL10, TNFα, and MIF were different between patients with baseline American Spinal Injury Association Impairment Scale (AIS) grades of A or B, whilst IL2 (>2 fold) and MIP-3a (>6 fold) were significantly expressed in the cervical and thoracic regions." (PMID 33806460, 2021).
Splenomegaly (1 paper, 2019). Abnormal increased size of the spleen. "The splenomegaly observed in L-Galf-treated mice could be related to T lymphocyte recruitment promoted by the enhanced expression of CXCL-11, and is supported by the influx of CD8 cells observed on tissue sections." (PMID 31870416, 2019).
systemic sclerosis (1 paper, 2024). A chronic disorder, possibly autoimmune, marked by excessive production of collagen which results in hardening and thickening of body tissues. "In Systemic Sclerosis (SSc), an autoimmune disorder characterized by important vascular impairments and multiorgan severe failure, CXCL10 and CXCL11 can discriminate those subjects developing SSc from an initial “lighter” condition of very early diagnosis of SSc (VEDOSS)." (PMID 39355618, 2024).
transient arthritis (1 paper, 2023). Arthritis that is not permanent. "We also found new biomarkers that correlated with reactogenicity, including transient arthritis (MCP-2, CXCL10, CXCL11, CX3CL1, MCSF, IL-15, OSM)." (PMID 38235127, 2023).
tumor (483 papers, 2006 to 2026). "Spatial and coculture analyses of these tumors demonstrated that the CD8+ T cell-associated chemokine CXCL11 drove estrogen-independent tumor growth." (PMID 41623177, 2026). "Elevated levels of CXCL9, CXCL10, and CXCL11 in ascitic fluid facilitate NK cell trafficking to tumor sites and are associated with impaired tumor progression." (PMID 41567203, 2025). "Elevated levels of CXCL11 were associated with anti-tumour immune responses and improved prognosis in colon cancer." (PMID 39780187, 2025). "Like CXCL9, CXCL10 and CXCL11 expression, HLA-DR expression on tumor cells is tightly linked to IFN-γ signaling." (PMID 38822345, 2024). "Bartlett’s group demonstrated that oncolytic VACVs encoding CCL5 or CXCL11 elicited potent anti-tumor immunity and enhanced therapeutic efficacy by attracting activated immune cells such as T (Th1) and NK cells." (PMID 38283361, 2023). "Remarkably, the closest association between the tumor stage and the expression of CXCL11 occurred in stage I and other stages." (PMID 35935945, 2022). "We analyzed the expression of CXCL11 in different stages of 33 tumors and found that CXCL11 expression was closely associated with tumor stage in 7 types of cancer, including COAD, HNSC, KIRC, KIRP, PAAD, SKCM, and THCA." (PMID 35935945, 2022). "CXCL11 expression was differentially associated with tumor stage in certain types of cancers, while the association of upregulated CXCL11 expression with OS, DSS, DFI, or PFI was inconsistent in other types of cancers." (PMID 35935945, 2022). "The association of CXCL10 and CXCL11 with diverse human conditions like immune dysfunction and tumour progression has been documented." (PMID 33960101, 2022). "Further analysis revealed that tumor infiltrating immune phenotype and neoantigen load were significantly elevated in tumors with high expression of CXCL11, which was closely linked to immunotherapeutic efficacy." (PMID 34047476, 2021). "A high level of CXCL11 was associated with worse Tumor Node Metastasis (TNM) staging in patients with PC, enhancing proliferation and metastasis in PC cells." (PMID 32341359, 2020). "FIP200 deletion induced an anti-tumor immune response mediated by CD8+ and CD4+ T cell infiltration to the tumor site, mediated by IFNγ and chemokine secretion (CXCL9, CXCL10, CXCL11) by autophagy-deficient tumor cells." (PMID 31554173, 2019). "The secretion of CXCL10 and CXCL11 by neuroendocrine-like cells can recruit tumor-associated macrophages to infiltrate in tumor tissues." (PMID 27034164, 2016). "In addition, oncolytic VACVs encoding CXCL11 can further enhance the anti-tumor effect of mesothelin-CAR T-cell therapy via CXCL11-mediated recruitment of T-cells." (PMID 38283361, 2023). "On the other hand, some chemokine signaling-related molecules (such as CXCL10 and CXCL11) were associated with better patient OS, and these chemokines secreted by pEMT-like tumor cells may promote the recruitment of IgG1 PCs via ACKR1." (PMID 37138324, 2023). "Stimulator of interferon genes (STING) upregulation in tumor APCs triggers chemokine expression, notably C-X-C motif chemokine ligand 9 (CXCL9) and CXCL10 by DCs, and CXCL10 and CXCL11 by tumor-associated macrophages (TAMs), folstering intratumoral T cell trafficking." (PMID 38044445, 2023). "Because of the diversity of receptors and the variants of its CXCR3 receptor, CXCL11 might contribute to tumor progression in certain types of cancers." (PMID 35935945, 2022). "For example, the presence of CXCL10 or CXCL11 within the tumor is associated with a CD8 T-cell number but also with the CD4 Treg cell accumulation with immunosuppressive and cancer-initiating effects, thus rendering it difficult to use such chemokines as prognostic factors." (PMID 36429101, 2022). "Moreover, CXCL11 is highly associated with tumor formation, progression, metastasis, and angiogenesis, as well as with the adverse effects of chemotherapy." (PMID 36504808, 2022).
tumor (continued). "In addition, the secretion of CXCL11 by neuroendocrine-like cells can recruit tumor-associated macrophages (TAMs) to infiltrate tumor tissues, which enhances the proliferation and invasion of CRC cells and leads to poor prognosis." (PMID 33777950, 2021). "Cancer cells cause CXCL11 secretion by regulating tumor stromal cells in the microenvironment." (PMID 32341359, 2020). "For example, in a colorectal cancer model neuroendocrine differentiation may induce the infiltration of tumour-associated macrophages (TAMs) attracted by CXCL-10 and CXCL-11 leading to enhanced tumour cell proliferation and invasion." (PMID 29157300, 2017). "E7046 + E7777 treatment activated the innate immune system which led to an “inflamed” TME evidenced by expression of genes encoding Ccl5/RANTES, macrophage inflammatory protein-1α (MIP-1α/Ccl3), Cxcl9, Cxcl10, and Cxcl11, previously found associated with tumor destruction." (PMID 28920002, 2017). "Moreover, components of the tumor stroma, such as endothelial cells, pericytes and cancer-associated fibroblasts, were capable of CXCL11 expression." (PMID 29163806, 2017). "Moreover, we confirmed that CXCL10 and CXCL11 are the key chemokines in neuroendocrine-like cells and they promote the chemotaxis activity of tumor-associated macrophages." (PMID 27034164, 2016). "Additionally, overexpression of CXCR3 is significantly associated with the tumor grade and lymph node metastasis, suggesting a role for CXCL11/CXCR3 in promoting ovarian carcinoma metastasis." (PMID 24384839, 2013). "In BPR20 tumors treated with ARG2i/COX2i/NOS2i, an increase in CD45+ immune cell infiltration into the tumor was observed, corresponding with increases in gene transcripts associated with immune cell-mediated tumor growth control and inflammation (e.g., Ccl21a, Fasl, Cd8b1, Cd40, Cd4, Cxcl11)." (PMID 38312842, 2024). "On the other hand, we demonstrated that monocytes infiltrating HT-29 spheroids may also possess anti-tumoral activities, as the secretion of CXCL10 and CXCL11, only secreted in HT-29 spheroids, and increasing upon monocyte addition, has been associated with tumor-suppressive functions." (PMID 34451433, 2021). "Such stromal expression pattern of CXCR7 and CXCL11 genes and their enrichment to mesenchymal OC subtype associated with worst prognosis support their contribution in the ability of the microenvironment to modulate cancer development, resulting in tumor dissemination." (PMID 30051594, 2018). "Moreover, in RCC, pervious studies found the expression of CXCL9, CXCL10 and CXCL11 increased in tumor compared to normal kidney tissues, suggesting the association with TILs and favorable prognosis, and the promotion of tumor specific immunity in systemic high-dose interleukin-2 (IL-2) therapy." (PMID 26910919, 2016). "In this study, C-X-C motif chemokine ligand 11 (CXCL11) was identified to be upregulated in tumor tissues of NPC patients and NPC cells compared to counterpart normal tissues and cell lines." (PMID 42077068, 2026). "Ectopically expressed DDX5 facilitated transcription factor STAT3 activation by resolving the RNA G-quadruplex structure of STAT3, resulting in a higher level of CXCL11 transcription and an increase in tumor-infiltrating CD8+ T cells." (PMID 40651961, 2025). "JASPAR prediction and ChIP-qPCR confirmed the recruitment of STAT4 to the enhancer region, leading to transcriptional upregulation of CXCL11 and subsequent NK cell infiltration, which exerted an anti-tumor effect." (PMID 40576244, 2025).